RN7SKP173 (RN7SK pseudogene 173)
Gene: Miscellaneous RNA gene on chromosome 20 (38,761,528 to 38,761,842, forward strand). Ensembl gene ENSG00000199691.
Homologues: Orthologues: chimpanzee 7SK (98% identical). Paralogues in human: 7SK (77% identical), RN7SKP255 (76% identical), RN7SKP79 (76% identical), RN7SKP102 (74% identical), RN7SKP30 (74% identical), RN7SKP71 (74% identical), RN7SKP180 (74% identical), RN7SKP294 (74% identical), RN7SKP124 (73% identical), RN7SKP170 (73% identical), RN7SKP185 (73% identical), RN7SKP77 (73% identical), and 283 more.